GSK3B (glycogen synthase kinase 3 beta)
Diseases named in the same sentence as GSK3B in open-access papers (continued):
Sharing a sentence is not in itself a finding about the gene and the disease.
hepatocellular carcinoma (continued). "Likewise, PRMT5-methylation of SREBP1, a transcription factor required for de novo lipogenesis, prevents its phosphorylation by GSK3β and subsequent ubiquitination by FBXW7, thereby increasing lipogenesis and tumor growth of hepatocellular carcinoma (HCC)." (PMID 32743345, 2020). "In addition, in both hepatocellular carcinoma (HCC) and prostate cancer cells, bFGF was shown to induce epithelial–mesenchymal transition through the AKT/GSK-3β/Snail signaling pathway." (PMID 31868203, 2020). "Recent studies with hepatoma cells have shown that imatinib inhibits c-Abl cytosolic tyrosine kinase to attenuate insulin-induced but not IGF-1-induced phosphorylation of Akt and GSK-3β." (PMID 19693287, 2009).
Cognitive impairment (185 papers, 2009 to 2026). Abnormal cognition is characterized by deficits in thinking, reasoning, or remembering. "Western blotting showed that RBX injections led to the overactivation of tau kinases PKA and GSK3β, resulting in hyperphosphorylated tau, neuronal loss, and cognitive impairments." (PMID 39592915, 2025). "Our previous studies have shown that T2DM patients carrying the ApoE4 allele exhibit increased activity of GSK‐3β in platelets and more severe cognitive impairment." (PMID 40905109, 2025). "Insulin secretion is primarily regulated by the PI3K-AKT-GSK/3 signaling pathway, where GSK-3β serves as a key protein associated with both cognitive impairment and glycemic regulation." (PMID 40417692, 2025). "Findings from a preclinical study showed that high-fat diet-induced cognitive impairment is mediated by stimulating neuronal GSK3β activity, which causes oxidative stress, mitochondrial dysfunction, and neuroinflammation." (PMID 40379890, 2025). "Activated GSK-3β has been reported to decrease long-term memory formation and cause cognitive impairment in the hippocampus." (PMID 38881175, 2024). "ATP‐competitive inhibitors indirubin, hymenialdisin, and SB216763 can inhibit GSK‐3β enzyme activity, alleviate Aβ deposition and tau hyperphosphorylation‐associated neuropathological changes, and improve cognitive impairment in AD animal models." (PMID 39129397, 2024). "Our research was one of the few articles to discuss the relationship between amylin and brain GSK-3β in improving cognitive disorders associated with T2DM." (PMID 38536493, 2024). "Recent studies have found that GSK-3β inhibitors can alleviate cognitive impairments associated with AD, prompting the initiation of clinical trials for potential drug candidates." (PMID 38473895, 2024). "Smek1 deficiency caused markedly more severe motor and cognitive impairments in mice, as well as neuronal loss, gliosis, and tau hyperphosphorylation at major glycogen synthase kinase 3β (Gsk3β) sites." (PMID 39206808, 2024). "Findings from preclinical studies showed that high‐fat diet (HFD)‐induced cognitive impairment in mice is mediated by triggering neuronal GSK3β activity which causes oxidative stress, mitochondrial dysfunction and neuroinflammation." (PMID 39644152, 2024). "The present findings supported earlier studies that cadmium-evoked cognitive deficit was linked to elevated hippocampal Bax, decreased Bcl-2, and activated GSK-3β." (PMID 37765022, 2023). "In this study, we used medium doses of GSK3β inhibitors, and previous studies reported that these dosages significantly inhibited GSK3β activity but rarely caused behavioral and cognitive deficits." (PMID 36949769, 2023). "Logistic regression analyses of the association between GSK‐3β activity and the risk of cognitive impairment." (PMID 37700547, 2023). "In a dementia mouse model, estrogen deficiency was shown to aggravate cognitive impairment through the ERβ/GSK-3β pathway." (PMID 36844418, 2023). "In this study, we investigated the effects of miR-132-3p-enriched MSC EX on neuron damage, synaptic dysfunction, and cognitive impairment in a VD mouse model and the underlying mechanism of action by analyzing the Ras/Akt/GSK-3β signaling pathway." (PMID 35841005, 2022). "Conditional expression of GSK-3β in the mouse brain decreased postsynaptic density number and reduced the volume in hippocampal granule neurons, a phenomenon associated with cognitive impairment." (PMID 35126052, 2021). "The GSK-3β signalling pathway has been recently implicated in the outer membrane vesicle-induced tau hyperphosphorylation, leading to cognitive impairment." (PMID 35010895, 2021). "It is known that GSK3-β activity is associated with AD neuropathology as it exacerbates cognitive impairment." (PMID 32050516, 2020).
Cognitive impairment (continued). "The hyperactivity of GSK-3β expressed in neurons causes cognitive impairment, tau hyperphosphorylation, increased β-amyloid production, neuronal death, and neuroinflammation leading to the occurrence of depression." (PMID 33658947, 2020). "For example, HFD feeding in another AD mouse model (APP23 mice) caused cognitive deficits and increased hippocampal and cortical Aβ deposition and insulin resistance was reported to increase hyperphosphorylation of Tau via GSK-3β activity." (PMID 33003412, 2020). "Several mechanisms associated with GSK3β appear to contribute to cognitive impairment, as detailed below." (PMID 29515352, 2018). "We have previously shown that amyotrophic lateral sclerosis (ALS) with cognitive impairment (ALSci) is associated with tau phosphorylation at Thr175 and that this leads to activation of GSK3β which then induces phosphorylation at tau Thr231." (PMID 28077166, 2017). "Specific cognitive deficits and tau-phosphorylation in residues associated to early AD stages were reversed by lithium chloride, a GSK-3β inhibitor." (PMID 25187954, 2014). "Interestingly, tau-deficient mice overexpressing GSK3β displayed reduced neurodegenerative symptoms and milder cognitive deficits, suggesting that the interaction between GSK3β and tau is critical for tau hyperphosphorylation and the development of AD." (PMID 39996845, 2025). "In addition, GSK3β overactivity is associated with microglial activation and inhibition of neurogenesis, resulting in cognitive impairment." (PMID 40379890, 2025). "In addition to AChE and COX-2, molecular docking was also performed on other molecular targets linked to cognitive impairment, including GSK-3β, BACE-1, and caspase-3." (PMID 39598743, 2024). "In an experiment conducted on 6- and 60-day-old male mice, testosterone was discovered to inhibit the interaction between tau and GSK3β in both cultured hippocampal neurons and neonatal mice, thereby attenuating the tau phosphorylation and cognitive impairment caused by sevoflurane." (PMID 39399315, 2024). "This extends the scope of potential applications of GSK3β inhibitors and suggests that chronic administration of GSK3β inhibitors maybe an option for treating behavioral and cognitive deficits associated with adolescent METH abuse in adulthood." (PMID 36949769, 2023). "Altogether, long-term HFD treatment promotes Tau phosphorylation via GSK-3β activation, which might be associated with cognitive deficits." (PMID 36615907, 2023). "We focus on the underlying AMPAR signaling cascades and GSK3β synaptic plasticity regulation in adolescent male and female mice to identify sex differences in the hippocampus that may underly cognitive deficits following MA abuse." (PMID 37842014, 2023). "GSK‐3β is activated in association with aging, inflammation, mild cognitive impairment, and AD." (PMID 35026860, 2022). "GSK-3β is one of the most important protein kinases implicated in the regulation of Aβ production and Tau phosphorylation, and related to neuronal dysfunction and cognitive impairment." (PMID 35841005, 2022). "The mechanisms associated with GSK3β that contribute to cognitive impairment are as follows." (PMID 29515352, 2018). "Various effects of lithium are caused by GSK-3β inhibition, and lithium administration reduces the neuropathology and cognitive deficits in rats that have received intra-hippocampal injections of Aβ, rats overexpressing GSK-3β, and several murine models overexpressing human APP." (PMID 24904272, 2014). "Activated JNK and GSK-3β downregulation may contribute to the downregulation of antioxidant proteins, thereby exacerbating synaptic dysfunction, neuroinflammatory responses, and cognitive deficits associated with neurodegeneration." (PMID 40771195, 2025). "Therefore, patients with aberrant GSK-3β activity may be the only ones for whom lithium treatment is effective against AD-associated cognitive impairments and neuropathology." (PMID 39200803, 2024).
Cognitive impairment (continued). "Rescuing synaptic ultrastructural abnormalities in the dHIP CA1 subregion by chronic administration of a GSK3β inhibitor may be a suitable therapeutic strategy for the treatment of behavioral and cognitive deficits in adulthood associated with adolescent METH abuse." (PMID 36949769, 2023). "Furthermore, Li has been reported to improve chronic mild stress-induced depressive and cognitive deficits in rodent models, as evidenced by reduced glycogen synthase kinase-3 beta (GSK3β) overexpression, which otherwise causes cortical neuroinflammation and tauopathy." (PMID 36055984, 2022). "Therefore, chronic administration of AM404 at low dose attenuated cognitive deficit and related pathological features associated with Akt/GSK3β pathway, which might be increased by the concentration of anandamide in plasma or brain." (PMID 30426182, 2019). "GSK-3β overexpression induces apoptosis and causes a reduction in postsynaptic density number and volume in hippocampal granule neurons, a phenomenon that may be related to cognitive impairment." (PMID 28109286, 2017). "GSK-3β overexpression induces apoptosis and causes a drastic decrease in postsynaptic density number and volume in hippocampal granule neurons, a phenomenon that may be related to cognitive impairment." (PMID 25644393, 2015). "Findings from preclinical study observed that metformin improves cognitive impairment in AD rat model by attenuating the development of brain insulin resistance through inhibition of GSK3β signaling." (PMID 40251348, 2025). "Our data support these findings by showing significant changes in GSK‐3β phosphorylation levels in ApoE4‐T2DM mice, highlighting the critical role of ApoE4 in mediating AD‐related pathological changes and cognitive impairments via GSK‐3β." (PMID 40905109, 2025). "The potential of PQQ in delaying aging is highly esteemed, as it can ameliorate D-galactose-induced cognitive impairment by attenuating glutamate neurotoxicity through the GSK-3β/Akt signaling pathway in mice." (PMID 40153371, 2025). "Inhibiting GSK‐3β efficiently mitigated the AD‐like pathologies and cognitive impairments in the ApoE4‐T2DM mice." (PMID 40905109, 2025). "In the AlCl3-treated group, there was a significant increase in GSK-3β level, indicating its role in AD-related cognitive deficits." (PMID 40748435, 2025). "The T2DM patients carrying the ApoE ε4 allele exhibit heightened activation of platelet glycogen synthase kinase‐3β (GSK‐3β), a key downstream kinase in the insulin signaling pathway, along with more severe cognitive deficits." (PMID 40905109, 2025). "Corroboratively, GSK3β inhibition in diverse mouse models has been shown to reduce tau phosphorylation and improve cognitive impairments measured through behavioral assays." (PMID 39996845, 2025). "Future studies should explore the mechanisms by which the interaction between ApoE4 and T2DM contributed to AD pathology and evaluate the impact of GSK‐3β inhibitors on cognitive impairments in T2DM populations." (PMID 40905109, 2025). "DJS ameliorates cognitive impairment by regulating Akt/GSK3β/β-catenin signaling and hippocampal estrogen synthesis." (PMID 38486385, 2025). "In transgenic models, overexpressing or chronically activating GSK3β induces tau pathology and cognitive deficits, whereas pharmacologically inhibiting GSK3β prevents those changes." (PMID 41031163, 2025). "We found that expressing ApoE4 upregulated GSK‐3β in the hippocampus and exacerbated AD‐like pathologies and cognitive impairment in T2DM mice." (PMID 40905109, 2025). "miR-23b-3p ameliorated cognitive deficits, inhibited cell apoptosis, and reduced tau hyperphosphorylation via the downregulation of GSK-3β signaling pathway." (PMID 38338859, 2024). "In the present study, Wnt/β-catenin/GSK-3β signaling pathway inhibition reversed the improvement effect of OTN on cognitive impairment and neuronal damage in SAH rats and blocked the promotion effect of OTN on NSC proliferation." (PMID 38596082, 2024).
Cognitive impairment (continued). "OTN improved cognitive impairment, abolished neuronal damage, and promoted neural stem cell proliferation via activating the Wnt/β-catenin/GSK-3β signaling pathway after SAH." (PMID 38596082, 2024). "Inhibiting GSK-3β activity has been shown to improve cognitive impairments and attenuate oxidative stress." (PMID 39081851, 2024). "We also identified the essential role of the PI3K/Akt/GSK-3β signal pathway in HCD-induced cognitive impairment." (PMID 39200168, 2024). "Inhibition of GSK3β activity was found to improve cognitive deficits and reduce oxidative stress response." (PMID 38851758, 2024). "These EVs can increase BBB permeability, activate astrocytes and microglia, trigger inflammatory responses, and induce tau hyperphosphorylation via the glycogen synthase kinase-3 beta (GSK-3β) pathway, ultimately leading to cognitive impairment." (PMID 39000150, 2024). "Clinical studies have also revealed a strong correlation between excessive activity of GSK-3β and cognitive impairment." (PMID 38660514, 2024). "In this study, we have demonstrated that 9‐MF significantly prevented cognitive impairments, Aβ‐associated microglial over‐activation, and tau‐associated synaptic damage via cell‐specific inhibition of ROCK2 and GSK3β." (PMID 39563011, 2024). "GSK‐3β activity is increased in patients with mild cognitive impairment, and GSK‐3β can inhibit neuronal axon regeneration in the central nervous system." (PMID 39129397, 2024). "Compelling evidence suggests that inhibition of GSK-3β activity by pharmacological treatment prevents cognitive impairment in transgenic AD mice." (PMID 36978877, 2023). "The results reveal a positive association of ApoE ε4 with cognitive decline in T2DM patients, and a mediative role of GSK‐3β activation between the ApoE ε4 and cognitive impairment." (PMID 37700547, 2023). "In summary, our results reveal that ApoE ε4 genotype was associated with cognitive dificits in Chinese Han T2DM patients, and GSK‐3β plays a mediative role between ApoE ε4 and cognitive impairment." (PMID 37700547, 2023). "We also found in the current cohort that T2DM patients with cognitive impairment (CI) showed elevated GSK‐3β activity compared with those with normal cognition (p < .0001)." (PMID 37700547, 2023). "We revealed in the present study through correlation and mediation analyses that ApoE ε4 can lead to cognitive impairments in T2DM patients by elevating GSK‐3β activity." (PMID 37700547, 2023). "Lastly, using Baron and Kenny modeling, we unveiled a mediative role of GSK‐3β activity between ApoE ε4 and cognitive impairment." (PMID 37700547, 2023). "When insulin signal transduction was impaired, AKT lost its inhibition of glycogen synthase kinase-3β (GSK3β), increased the expression of Aβ and Tau, and further aggravated cognitive impairment." (PMID 37152933, 2023). "Chronic administration of curcumin, the main active ingredient in turmeric, alleviates AD-associated cognitive impairments via upregulating BDNF/ERK and Akt/GSK3β signaling in the hippocampus." (PMID 35090576, 2022). "Recent studies found that inhibition of Gsk3β activity alleviated cognitive deficits and activated the Nrf2 pathway in SAMP8 mice." (PMID 36065437, 2022). "From the identified BDNF/GSK-3β/β-catenin axis, dysfunction of Wnt signaling is enough to encourage a neuropathological process incorporated in AD as cognitive impairment and aggregation of Aβ." (PMID 35668264, 2022). "Silibinin reduced the expression of phosphorylated GSK3β (Y216) in formaldehyde-induced cognitive impairment mice." (PMID 35757504, 2022). "Studies have shown that GSK-3β is related to the apoptosis of nerve cells, the atrophy of nerve protrusions, and cognitive impairment." (PMID 34839794, 2021). "After 3 weeks of oral gavage with IRN (20 or 40 mg/kg/day), Aβ25-35-induced cognitive impairment was improved in rats, and inhibition of GSK3β activity was one of the mechanisms." (PMID 34975502, 2021).